SLC32A1 (solute carrier family 32 member 1)
Description:
Antiporter that exchanges vesicular protons for cytosolic 4-aminobutanoate or to a lesser extend glycine, thus allowing their secretion from nerve terminals. The transport is equally dependent on the chemical and electrical components of the proton gradient (By similarity). May also transport beta-alanine (By similarity). Acidification of GABAergic synaptic vesicles is a prerequisite for 4-aminobutanoate uptake (By similarity).
Synonyms: VGAT; VIAAT; bA122O1.1; DEE114; GEFSP12; VIAAT GEFSP12
Tractability: Antibody: its Gene Ontology location is reachable by antibodies, with high confidence; UniProt predicts a signal peptide or a membrane-spanning region. PROTAC: its protein half-life has been measured.
Gene: Protein-coding gene on chromosome 20 (38,724,486 to 38,729,372, forward strand). Ensembl gene ENSG00000101438.
Subcellular location: Cytoplasmic vesicle membrane; Presynapse
Subcellular location (Human Protein Atlas): Cytosol
Pathways (Reactome):
Neuronal System: GABA synthesis, release, reuptake and degradation
Transport of small molecules: SLC-mediated transport of neurotransmitters
Gene Ontology:
Molecular function: amino acid transmembrane transporter activity; gamma-aminobutyric acid transmembrane transporter activity; gamma-aminobutyric acid:proton antiporter activity; gamma-aminobutyric acid:proton symporter activity; glycine transmembrane transporter activity; glycine:proton antiporter activity
Biological process: beta-alanine transport; gamma-aminobutyric acid import; gamma-aminobutyric acid transport; glycine transport; neurotransmitter loading into synaptic vesicle; neurotransmitter secretion; neurotransmitter transport; amino acid transmembrane transport; hippocampus development; proton transmembrane transport
Cellular component: dendrite; neuron projection; neuron projection terminus; clathrin-sculpted gamma-aminobutyric acid transport vesicle membrane; cytoplasmic vesicle membrane; dendrite terminus; plasma membrane; presynapse; synaptic vesicle; synaptic vesicle membrane; cell surface; cell tip; cone cell pedicle; GABA-ergic synapse; inhibitory synapse; presynaptic active zone; synapse
Genetic constraint (gnomAD): Loss-of-function variants: 8 observed, 36.45 expected, observed/expected ratio (o/e) 0.22, 90% interval 0.13 to 0.4. The upper end of that interval is the gene's LOEUF score, 0.4, which puts it in group 1 of 6, group 1 being the genes least tolerant of losing a copy. Missense variants: 493 observed, 752.91 expected, observed/expected ratio (o/e) 0.65, 90% interval 0.61 to 0.7. Synonymous variants: 317 observed, 347.58 expected, observed/expected ratio (o/e) 0.91, 90% interval 0.83 to 1.
Homologues: Orthologues: chimpanzee SLC32A1 (99% identical), macaque SLC32A1 (99% identical), guinea pig SLC32A1 (99% identical), dog SLC32A1 (98% identical), mouse Slc32a1 (98% identical), pig SLC32A1 (98% identical), rat Slc32a1 (98% identical), tropical clawed frog slc32a1 (89% identical), zebrafish slc32a1 (87% identical), rabbit SLC32A1 (75% identical), Drosophila melanogaster VGAT (42% identical), Caenorhabditis elegans unc-47 (35% identical), and 15 more. Paralogues in human: SLC38A6 (19% identical), SLC38A5 (18% identical), SLC38A3 (18% identical), SLC38A4 (17% identical), SLC38A2 (16% identical), SLC36A1 (16% identical), SLC38A7 (16% identical), SLC36A2 (16% identical), SLC36A4 (16% identical), SLC38A1 (16% identical), SLC36A3 (15% identical), SLC38A10 (13% identical), and 3 more.
Diseases named in the same sentence as SLC32A1 in open-access papers:
SLC32A1 is named in the same sentence as 63 diseases in open-access papers, as found by Europe PMC text mining. Sharing a sentence is not in itself a finding about the gene and the disease. The quoted sentences say what the papers report.
depression (11 papers, 2013 to 2023). "The decreased expressions of mRNAs in CUMS-induced depression mice include Slc6a11, Hap1, Gad1, Gad2, Gng4, Slc32a1, Doc2g, Slc32a1, Magel2, Prkcd, Ngfr, Dusp1, Th, Itih3, Cacna2d2, Arc, Mbp, Peg10, Fos, and so on." (PMID 27427907, 2016). "The LIMMA analysis first detected a number of down-regulated genes in individuals with EDs that are known to be suppressed in schizophrenia or major depressive disorder, such as SST, NPY, SLC32A1, HINT1, and RELN." (PMID 29958387, 2018).
epilepsy (10 papers, 2013 to 2026). A brain disorder characterized by episodes of abnormally increased neuronal discharge resulting in transient episodes of sensory or motor neurological dysfunction, or psychic dysfunction. "Previous studies have discovered that missense mutations in SLC32A1 lead to epilepsy and neurodevelopmental disorders through two mechanisms: altering synaptic vesicle filling and regulating synaptic short-term plasticity." (PMID 38390494, 2024).
schizophrenia (9 papers, 2016 to 2024). A major psychotic disorder characterized by abnormalities in the perception or expression of reality. "Furin, a protein affecting inhibitory synaptic transmission by altering the transcription of GABAA receptor subunits, has been implicated in schizophrenia GWASs along with chloride channel CLCN3 and vesicular inhibitory amino acid transporter SLC32A1, involved in GABA uptake into synaptic vesicles." (PMID 36833173, 2023). "In addition, multiple candidate genes implicated in schizophrenia or other psychiatric disorders were detected, such as SST, NPY, SLC32A1, HINT1, RELN, and IFITM3." (PMID 29958387, 2018).
Obesity (5 papers, 2012 to 2019). Accumulation of substantial excess body fat. "These SNPs were in/near the following genes: LEP, SLC32A1 (solute carrier family 32 member 1), GCKR (glucokinase regulatory protein), CCNL1 (cyclin-L1), and FTO (fat mass and obesity-associated)." (PMID 31766143, 2019).
glioma (3 papers, 2020 to 2025). A benign or malignant brain and spinal cord tumor that arises from glial cells (astrocytes, oligodendrocytes, ependymal cells). "Using the first CGGA dataset, 14 samples were classified as NL gliomas with both SLC32A1/MSR1 and C5AR1/SYT5 gene signatures vs 263 OT samples." (PMID 33059718, 2020). "A machine learning-based approach identified C5AR1/SYT5 and MSR1/SLC32A1 signatures which were able to discriminate NL IDH-WT gliomas with high sensitivity and specificity in various glioma expression datasets." (PMID 33059718, 2020). "We identified two gene signatures composed of SLC32A1/MSR1 and SYT5/C5AR1 gene combinations whose expression alone strongly correlated with this subgroup of IDH-WT gliomas." (PMID 33059718, 2020). "In contrast, the SLC32A1 and SYT5 genes were underexpressed in the OT cluster and in higher-grade gliomas." (PMID 33059718, 2020).
childhood absence epilepsy (1 paper, 2011). A familial generalized pediatric epilepsy, characterized by very frequent (multiple per day) absence seizures, usually occurring in children between the ages of 4 and 10 years, with, in most cases, a good prognosis. "Regarding the modulators of GABAergic transmission, the major FS hubs are GABRB3, a gene coding a GABAA receptor subunit and in which mutations are known to cause childhood absence epilepsy, and SLC32A1, that codes for a vesicular GABA transporter." (PMID 22022585, 2011).
Fever (1 paper, 2024). Body temperature elevated above the normal range. "The LPS-induced fever was significantly different in NtsSlc32a1-/- mice when compared with that of wild-type littermates Ntscre Slc32a1+/+." (PMID 39207910, 2024).
nicotine addiction (1 paper, 2018). "In addition to the GABA pathway, Slc32a1 is mapped to the morphine addiction, nicotine addiction, and endocannabinoid signaling pathways." (PMID 30618656, 2018).
pancreatic cancer (1 paper, 2024). "SLC32A1 is aberrantly methylated in pancreatic cancer and has been identified as an NF-κB-inducible gene." (PMID 38542061, 2024).
Tremor (1 paper, 2020). An unintentional, oscillating to-and-fro muscle movement about a joint axis. "As our model is constitutive and Slc32a1 is removed from Purkinje cells throughout the cerebellum, it does not mimic the progressive loss of Purkinje cells or a localized insult to cerebellar circuitry that has been associated with some manifestations of tremor in humans." (PMID 32180549, 2020).
infection (4 papers, 2021 to 2023). The state of being infected such as from the introduction of a foreign agent such as serum, vaccine, antigenic substance or organism. "Many solute carrier (SLC) family genes were also activated at 24 or 48 h after infection, including SLC16A12, SLC2A3, SLC16A6, and SLC32A1." (PMID 37211158, 2023).
psychiatric disorder (3 papers, 2017 to 2025). A disorder characterized by behavioral and/or psychological abnormalities, often accompanied by physical symptoms. "The overlapped PTSD DEPs include downregulated GABAergic genes SLC32A1, NEGR1, and PACSIN1, which we consider are high-confidence PTSD DEPs, especially NEGR1 which is also a risk gene for multiple psychiatric disorders including MDD and SCZ." (PMID 40301990, 2025).
SLC32A1 also shares sentences with these, for which no sentence is quoted: Anxiety (14 papers); ischemia (4); Stroke (4); tumor (4); Tinnitus (3); cognitive defects (2); cortical dysplasia (2); Epileptic encephalopathy (2); Alzheimer disease (1); Arrhythmia (1); Ataxia (1); Atrophy (1); AV block (1); brain ischemia (1); breast carcinoma (1); cancer (1); Cataplexy (1); cleft palate (1); colon cancer (1); COVID-19 (1); dementia (1); demyelination (1); diabetes (1); Dravet syndrome (1); Dystonia (1); Encephalopathy (1); Focal cortical dysplasia (1); glaucoma (1); hearing loss (1); hippocampal atrophy (1).
A further 21 diseases each share a sentence with SLC32A1 in 1 paper.